INS (insulin)
Diseases named in the same sentence as INS in open-access papers (continued):
Sharing a sentence is not in itself a finding about the gene and the disease.
Obesity (continued). "The C57BL/6 mouse strain has been shown to become obese, insulin resistant and glucose intolerant in response to consumption of a high (58%–60%) fat diet and is the most used model for studying diet induced obesity and its co-morbidities." (PMID 23201760, 2012). "In this study we have examined the effect of dietary curcumin in a HFD mouse model in which the development of obesity and insulin insensitivity was relatively slow due to the administration of 45% rather than 60% of calories from fat." (PMID 22253696, 2012). "The paradoxical reduction of dopamine function associated with obesity despite reduced sensitivity to leptin/insulin is likely a (pathological) adaptation as well, as frequently proposed in theories likening obesity to addiction." (PMID 22833718, 2012). "In other species, increased production of pro-inflammatory cytokines during obesity is known to directly influence decreased insulin sensitivity, thus evidence of this relationship in horses has been evaluated." (PMID 26486919, 2012). "The activity of both IκB-kinase β (IKKβ) and JNK is elevated in metabolic tissues in obesity, and these kinases are important nodes in the production of inflammatory mediators and in the desensitization of insulin signaling." (PMID 23316186, 2012). "The aim of the present study was to evaluate the antiobesity effects of the Chinese herbal formulation, LWDH, by measuring body weight, food intake, body fat mass, blood lipid profiles, and the hormones leptin and insulin using a rat model of obesity." (PMID 21904565, 2012). "For example, administration of both, PPARα agonists such as fibrates and FGF21 lowered LDL-cholesterol, raised HDL-cholesterol, improved insulin sensitivity and prevented diet-induced obesity in rhesus monkeys and rodents." (PMID 22394566, 2012). "Our findings are consistent with the known inter-relationship of obesity, physical activity, insulin, sex hormones and SHBG." (PMID 23113944, 2012). "Here, we extent the beneficial action of PLC treatment on the insulin-resistant state even when obesity had already been well established." (PMID 22457831, 2012). "Similar anti-obesity effects have been documented in mice subjected to a high fat and high fructose diet where insulin sensitivity and inflammation were also improved by astaxanthin." (PMID 23201837, 2012). "With the onset of insulin and leptin resistance, changes occur in several other obesity-related blood biomarkers, such as an increase in NEFA and triglyceride (TG) levels in the circulation, as well as in the liver and muscle tissues." (PMID 21904565, 2012). "In contrast to adipose tissue, the liver undergoes an obesity-induced activation of inflammation mainly within cells of the liver, including the resident macrophage-like Kupffer cells that crucially affect insulin sensitivity." (PMID 22272317, 2012). "The mutant mice were slimmer with increased insulin sensitivity and showed resistance to high-fat-diet induced obesity compared with wide-type mice." (PMID 23039759, 2012). "The pleiotropic role of SHP can also be found in the case of nonalcoholic liver steatosis since OB/SHP double (−/−) mice (a model of severe obesity and insulin resistance) became resistant to liver steatosis and showed improved insulin sensitivity." (PMID 22577560, 2012). "Mice without RIP140 are lean with increased oxygen consumption and are resistant to high-fat diet-induced obesity and hepatic steatosis with an improved insulin sensitivity." (PMID 23304112, 2012). "To date, some RXRα modulators have been reported to exhibit glucose-lowering, insulin-sensitizing or anti-obesity effects." (PMID 22384078, 2012). "Although this preliminary study found the potential to improve insulin sensitivity by starch type, several researchers reported that DAG, specifically the 1,3-DAG isomer, also elicits a positive effect on insulin sensitivity in addition to obesity reduction." (PMID 23762590, 2012).
Obesity (continued). "Together, our observations confirm that curcumin improves insulin signaling, glucose disposal, and blocks obesity during HFD consumption." (PMID 22253696, 2012). "FGF21 has been recognized as a hormonal regulator that reduces plasma glucose and TAG concentrations, enhances insulin sensitivity, and inhibits development of obesity and hepatosteatosis." (PMID 22394566, 2012). "Generally, obesity leads to higher demand for insulin production and the same is met by increase in beta cell mass." (PMID 22715406, 2012). "This association remained significant after adjusting for BMI as an overall marker of obesity, and for other confounding factors related to metabolic syndrome including glucose, insulin, total cholesterol, triglycerides, HDL-cholesterol, and blood pressure." (PMID 22952699, 2012). "Despite roles as both a domestic food animal of worldwide economic importance and a widely used model organism with relevance for human obesity and insulin resistance, few studies have examined regulation of gene expression in chicken adipose tissue." (PMID 22938590, 2012). "This situation is similar to mice, where a high (50%) sucrose diet leads to obesity but minimal insulin resistance, and somewhat different from larval Drosophila where high sucrose feeding promotes rapid insulin resistance." (PMID 22570630, 2012). "Studies have suggested that supplementation of these components can help ameliorate high fat-induced inflammation, obesity, glucose intolerance, and insulin insensitivity." (PMID 23363995, 2012). "Activation of p70S6K, and inhibition of 4EBP1 in pancreatic β-cells in murine models of DM, results in improved insulin secretion and resistance to β-cell streptozotocin toxicity and obesity." (PMID 23203037, 2012). "This phenomenon was accompanied by an improved glucose tolerance and insulin sensitization in a diet-induced obesity model (C57BL6/J)." (PMID 22952571, 2012). "Hyperuricemia has been linked with MetS and with criteria of MetS including glucose, insulin, blood pressure, obesity, waist circumference, waist-hip ratio, BMI, and lipid levels." (PMID 28348676, 2012). "The Wistar fatty rat exhibits obesity, hyperinsulinemia, hyperlipidemia, and hyperphagia, however they are more insulin resistant." (PMID 22257465, 2012). "Our results indicate that EDCs, such as BPA, BPAF, or Zea, are not only able to act as ER agonists but also as antagonists, with effects that are dose- and cell-dependent; this supports the results of experimental studies on insulin secretion and obesity." (PMID 22494775, 2012). "Both FGF19 and FGF21 transgenic mice are resistant to diet-induced obesity, have decreased adiposity and improved insulin sensitivity, glucose disposal, and plasma lipid profiles." (PMID 22457778, 2012). "It has been reported that UCP2 negatively regulates insulin secretion and is a major link between obesity, β-cell dysfunction, and T2DM." (PMID 22110477, 2012). "The mechanism by which vitamin D deficiency causes MetS in patients with CKD is likely multifactorial with abnormalities in glucose and insulin metabolism, obesity, hypertension and dyslipidemia all playing a role." (PMID 22784560, 2012). "Deficiency of JNK1 but not JNK2 was reported to result in reduced adiposity and steatohepatitis as well as improved insulin sensitivity in mouse models of obesity." (PMID 23139803, 2012). "In the context of obesity, the relationship between leptin/insulin, dopamine and reward behavior is paradoxical and doesn't conform to the idea just outlined." (PMID 22833718, 2012). "In parallel to the insulin levels, fasting plasma amylin levels are increased in patients with early type T2D and obesity, suggestive of a state of amylin resistance." (PMID 22619730, 2012). "By contrast, antisense oligonucleotides, which lower PTP1B levels only in adipose tissue and liver, reduce diet-induced obesity and improve insulin signaling in obese (ob/ob) and diabetic (db/db) mice." (PMID 22389718, 2012).
Obesity (continued). "Or is it the over-riding presence of obesity which drives inflammation to impair insulin signaling mechanisms and confer insulin resistance ?" (PMID 22462579, 2012). "Our current study identifies a novel role for the A2bAR in the context of T2D, including insulin and glucose homeostasis, chronic inflammation and obesity under HFD." (PMID 22848385, 2012). "The reduced cell death and inflammatory responses, as well as reduced obesity in CD36 KO mice were accompanied by improved insulin sensitivity, as recently reported by others." (PMID 22615812, 2012). "As consequences of obesity, a fatty liver and adipocyte hypertrophy play crucial roles in the development of metabolic syndrome via multiple mechanisms including impaired insulin signalling and inflammation." (PMID 22762794, 2012). "Reduced sensitivity to leptin/insulin is widely believed to arise as a consequence of chronic positive energy balance, leading to obesity and metabolic disorders, and representing a pathological adaptation." (PMID 22833718, 2012). "Global PTP1B deletion improves diet-induced obesity and glucose homeostasis via enhanced leptin signaling in the brain and increased insulin signaling in liver and muscle." (PMID 22389718, 2012). "It is well known that obesity and insulin sensitivity have a modulatory effect on the detection of genetic susceptibility for T2D." (PMID 22768041, 2012). "At least two adipocytokines, leptin and visfatin, as well as insulin, are elevated in obesity and are known to increase eNOS." (PMID 22505944, 2012). "Suppressor of cytokine signaling 3 (SOCS3) is a major negative regulator of both leptin and insulin signaling, thereby implicating SOCS3 in the pathogenesis of obesity and associated metabolic abnormalities." (PMID 23115649, 2012). "Knockout mice lacking betaine-homocysteine methyltransferase (BHMT), one of the enzymes that remethylate homocysteine to methionine, have increased energy expenditure and insulin sensitivity, and are resistant to diet-induced obesity." (PMID 22984471, 2012). "Such diet resembles the pathophysiologic scenario of what is known as ‘westernized diet’, which in addition to the sedentary life style is indicted for the widespread of obesity/insulin resistant cases nowadays." (PMID 22649556, 2012). "Various explanations are plausible, such as coexistence of obesity, lipotoxicity, activation of renin-angiotensin system and cardiac insulin resistance." (PMID 22347376, 2012). "Data is emerging on the transgenerational effects of maternal obesity and diet, with maternal diet influencing body length and insulin sensitivity in second and third generation mice." (PMID 23002417, 2012). "The TSOD-MF group showed increased food intake, obesity with predominant accumulation of visceral fat, insulin resistance and other metabolic complications, as compared with the TSNO-MF group." (PMID 21607011, 2011). "Epigenetic factors also regulate feeding behavior and metabolic phenotypes such as obesity and insulin sensitivity." (PMID 21526203, 2011). "Another study showed that intake of argan oil, improves insulin signaling in fat and liver beyond levels found in a rat model of dietary-induced obesity." (PMID 22114593, 2011). "There is sufficient evidence to suggest that resveratrol improves insulin sensitivity, reduces blood glucose levels, and reduces high fat diet-induced obesity in rodents." (PMID 21698226, 2011). "Mice lacking MARK2 have an increased rate of glucose disposal in response to exogenous insulin, increased glucose tolerance, and are resistant to diet-induced obesity." (PMID 22206009, 2011). "Because leptin has a certain degree of influence on appetite, energy consumption, adipose synthesis, and insulin function, elevated serum leptin levels are common in human obesity." (PMID 21526991, 2011). "Deletion of FABP5 resulted in a mild increase in systemic insulin sensitivity in genetic and dietary obesity mouse models." (PMID 22121495, 2011).
Obesity (continued). "The cytokine is over-expressed in adipose tissue of different models of obesity and known to inhibit insulin signalling." (PMID 21826222, 2011). "HFD-induced obesity has become widely accepted as a key factor of alteration in insulin sensitivity and metabolism." (PMID 22166251, 2011). "The purpose of the present study is to deepen into the understanding of caveolin regulation in conditions of diet-induced obesity and insulin resistance, and their relation to insulin signalling in skeletal muscle and adipocytes." (PMID 21489269, 2011). "In obesity, multiple stress kinases have been identified that impair the insulin signaling pathway via serine phosphorylation of key second messenger proteins." (PMID 21589939, 2011). "Most recently BAs were also found to activate the G-protein coupled receptor TGR5 and thereby exert anti-obesity as well as insulin sensitizing effects." (PMID 22110577, 2011). "Metabolic syndrome components (obesity, insulin and glucose insensitivity and hypertension) have been identified in offspring derived from a range of different maternal gestational nutritional challenges." (PMID 22194901, 2011). "BMPR2 mRNA expression correlated with measures of obesity and fat distribution, as well as with traits of glucose metabolism and insulin sensitivity." (PMID 21311592, 2011). "In summary, our data demonstrated that oral treatment with GABA inhibited the HFD-induced obesity and improved glucose intolerance and insulin sensitivity, even after the establishment of obesity and T2DM in mice." (PMID 21966503, 2011). "Collectively, these results indicate that intake of sucrose and hence increased insulin secretion, abrogates the protective effects of fish oil in relation to adipocyte hyperplasia and hypertrophy and thereby the development obesity." (PMID 21738749, 2011). "The FABP4 inhibitor, BMS309403, improved glucose metabolism and enhanced insulin sensitivity in both dietary (high fat-fed) and genetic (ob/ob) mouse models of obesity and diabetes." (PMID 22121495, 2011). "Vaspin is highly expressed in rat adipocytes from visceral WAT at the age when obesity and insulin plasma concentrations reach a peak." (PMID 21526992, 2011). "Administration of the anti-resistin antibody improves blood sugar and insulin action in mice with diet-induced obesity." (PMID 21686173, 2011). "Although we were unable to demonstrate a significant link between diet and obesity, we did detect a positive relationship between better micronutrient intake and lower blood pressure or higher insulin sensitivity (unpublished data)." (PMID 22166095, 2011). "In muscle, the expression levels of ADIPOR1 and ADIPOR2 correlated positively with obesity, glucose and insulin levels and insulin resistance." (PMID 21943112, 2011). "In obesity, macrophage infiltration of the expanding adipose tissue renders adipocytes insulin-resistant, consequently elevating circulating fatty acids and inflammatory cytokines that in turn contribute to insulin resistance in skeletal muscle." (PMID 22046423, 2011). "The various studies reported several specific drug offers: sildenafil, benzodiazepines, painkillers, antibiotics, insulin, female hormones, antidepressants, alopecia medications, and obesity medications." (PMID 21965220, 2011). "These medications act to reduce insulin levels (metformin) and increase insulin sensitivity (metformin and thiazolidenediones), thus treating the metabolic co-morbidities associated with PCOS and obesity." (PMID 21899727, 2011). "Candidate genes associated with metabolic syndrome phenotypes largely reflect current knowledge of established pathways regulating obesity, free fatty acid metabolism, insulin sensitivity, lipid metabolism, and inflammation." (PMID 22022282, 2011). "The hyperbolic relationship suggests that an environmental change in insulin sensitivity (i.e. obesity, exercise) will be well compensated by a change in insulin secretion." (PMID 21479217, 2011).
Obesity (continued). "Insulin-resistant persons, such as those with obesity, would also be likely to experience a more long-lasting plasma volume expansion with an ensuing risk of hemodynamic stress." (PMID 21966300, 2011). "This leads to dysregulation of anorexigenic effects of leptin and insulin, and initiation and progression of obesity." (PMID 22035457, 2011). "Obesity displays characteristics of a metabolic syndrome, with hyperinsulinemia and resistance to insulin, leading to type II diabetes, atherosclerosis, hypertension, hepatic steatosis, and sometimes cancer." (PMID 22087859, 2011). "DGAT1 knock out (-/-) mice are lean, resistant to diet induced obesity and have increased insulin sensitivity, while the DGAT2 (-/-) genotype is lethal." (PMID 22073239, 2011). "Activation of insulin signaling is crucial for the development of obesity and insulin receptor substrate-1 (IRS-1) transgenic mice are obese." (PMID 21738749, 2011). "Adult β-cell mass is known to be dynamic and to be able to respond to physiological changes in insulin demand such as obesity, pregnancy, and starvation." (PMID 22007286, 2011). "Visceral adipose tissue is also thought to be not only metabolically more active than subcutaneous, showing higher insulin-stimulated glucose uptake, but also more intensely affected by obesity-related inflammation and oxidative stress." (PMID 21489269, 2011). "Neurons from animals with diet-induced obesity also displayed inherent physiological changes as reflected in their altered firing patterns both under basal conditions and in response to acute insulin stimulation." (PMID 21966386, 2011). "The physiological implications of a dysregulation of insulin in obesity, CAD, and HT are well known." (PMID 21291537, 2011). "Epigenetic factors also influence feeding behavior and metabolic phenotypes, such as obesity and insulin sensitivity." (PMID 21526203, 2011). "Multivariate analysis in the present study showed that fasting insulin and cholesterol were independent predictors for obesity." (PMID 22044490, 2011). "Changes in evoked firing properties in mitral cells following IND insulin application and diet-induced obesity." (PMID 21966386, 2011). "The gene-activation mechanisms correcting disturbed ER functions eliminate ER stress that links atherosclerosis, obesity, insulin action and DM2." (PMID 21568932, 2011). "Obesity affects cardiovascular parameters such as left ventricular (LV) mass and cardiac function as well as metabolic parameters such as insulin levels and glucose tolerance." (PMID 21911326, 2011). "Multiple linear regression analysis showed that fasting insulin and cholesterol are independent predictors for obesity among CHC and HCC patients (OR: 1.663, p < 0.001, OR: 1.052, p < 0.001 respectively)." (PMID 22044490, 2011). "Visfatin has been proposed as an insulin-mimicking adipocytokine, predominantly secreted from adipose tissue and correlated with obesity." (PMID 21694775, 2011). "Further, obesity and high insulin levels are adverse prognostic factors for a number of cancers particularly those of the breast, prostate and colon." (PMID 21470407, 2011). "There is evidence to suggest that insulin and the IGF axis play an important role in mediating obesity associated malignancy." (PMID 21696633, 2011). "Conversely, bromocriptine treatment tended to reduce bodyweight and voluntary activity, and reinforce insulin action in DIO mice.These results show that DRD2 activation partly redirects high fat diet induced metabolic anomalies in obesity-prone mice." (PMID 21603181, 2011). "Recent data have revealed that the plasma concentrations of inflammatory mediators, such as TNF-α, MCP-1 and IL-6, are increased in the insulin resistant states of obesity." (PMID 21589925, 2011). "We have previously demonstrated that Kv1.3 is a target of insulin phosphorylation that exhibits resistance to phosphorylation following obesity." (PMID 21966386, 2011).